ATP2A3 (ATPase sarcoplasmic/endoplasmic reticulum Ca2+ transporting 3)
Description:
This magnesium-dependent enzyme catalyzes the hydrolysis of ATP coupled with the transport of calcium. Transports calcium ions from the cytosol into the sarcoplasmic/endoplasmic reticulum lumen. Contributes to calcium sequestration involved in muscular excitation/contraction.
Synonyms: SERCA3
Tractability: Small molecule: a drug acting on it is in phase 2 or 3 trials; a high-quality ligand is known; it belongs to a druggable protein family. Antibody: UniProt predicts a signal peptide or a membrane-spanning region. PROTAC: ubiquitination databases record sites on it; its protein half-life has been measured; a small molecule that binds it is known.
Target class: Enzyme; Hydrolase
Gene: Protein-coding gene on chromosome 17 (3,923,866 to 3,964,491, reverse strand). Ensembl gene ENSG00000074370.
Subcellular location: Nucleus membrane; Endoplasmic reticulum membrane; Sarcoplasmic reticulum membrane
Pathways (Reactome):
Hemostasis: Reduction of cytosolic Ca++ levels
Muscle contraction: Ion homeostasis
Signal Transduction: Pre-NOTCH Processing in Golgi
Transport of small molecules: Ion transport by P-type ATPases
Gene Ontology:
Molecular function: calcium channel regulator activity; calcium ion transmembrane transporter activity; calcium-dependent ATPase activity; cysteine-type endopeptidase activator activity involved in apoptotic process; P-type calcium transporter activity; protein binding; transmembrane transporter binding; ATP binding; ATP hydrolysis activity; nucleotide binding
Biological process: calcium ion transmembrane transport; calcium ion transport from cytosol to endoplasmic reticulum; intracellular calcium ion homeostasis; intrinsic apoptotic signaling pathway in response to endoplasmic reticulum stress; calcium ion transport; monoatomic ion transmembrane transport; regulation of cardiac conduction; transport across blood-brain barrier
Cellular component: endoplasmic reticulum; endoplasmic reticulum membrane; nuclear membrane; organelle membrane; sarcoplasmic reticulum; sarcoplasmic reticulum membrane; platelet dense tubular network membrane; membrane
Genetic constraint (gnomAD): Loss-of-function variants: 61 observed, 99.5 expected, observed/expected ratio (o/e) 0.61, 90% interval 0.5 to 0.76. The upper end of that interval is the gene's LOEUF score, 0.76, which puts it in group 3 of 6, group 1 being the genes least tolerant of losing a copy. Missense variants: 1,195 observed, 1,408.9 expected, observed/expected ratio (o/e) 0.85, 90% interval 0.81 to 0.89. Synonymous variants: 609 observed, 602.49 expected, observed/expected ratio (o/e) 1.01, 90% interval 0.94 to 1.08.
Homologues: Orthologues: chimpanzee ATP2A3 (99% identical), mouse Atp2a3 (95% identical), rat Atp2a3 (94% identical), dog ATP2A3 (93% identical), guinea pig ATP2A3 (93% identical), rabbit ATP2A3 (92% identical), pig ATP2A3 (91% identical), macaque ATP2A3 (85% identical), tropical clawed frog atp2a3 (80% identical), zebrafish atp2a3 (77% identical), Caenorhabditis elegans sca-1 (69% identical), Drosophila melanogaster SERCA (67% identical). Paralogues in human: ATP2A2 (77% identical), ATP2A1 (76% identical), ATP2C1 (34% identical), ATP2C2 (33% identical), ATP2B1 (30% identical), ATP2B3 (30% identical), ATP1A2 (30% identical), ATP1A4 (29% identical), ATP2B4 (29% identical), ATP1A1 (29% identical), ATP1A3 (29% identical), ATP2B2 (29% identical), and 9 more.
Diseases named in the same sentence as ATP2A3 in open-access papers:
ATP2A3 is named in the same sentence as 78 diseases in open-access papers, as found by Europe PMC text mining. Sharing a sentence is not in itself a finding about the gene and the disease. The quoted sentences say what the papers report.
breast carcinoma (12 papers, 2019 to 2025). "ATP2A3 has been reported to have associations with severe corona virus disease 2019 heart failure, breast cancer, Parkinson’s disease, bipolar disorder, white spot disease, and muscular atrophic disease (31, –, 33)." (PMID 40029616, 2025). "For example, the expression level of ATP2A1 and ATP2A3 in breast cancer is significantly higher and closely related to the malignant progression of the tumor, leading to a reduction in the survival time of patients." (PMID 35783262, 2022). "It has been proven that butyrate-treated cells increase Sp1 and Sp3 occupation at the ATP2A3 promoter and increase ATP2A3 mRNA expression in gastric and breast cancer cell lines." (PMID 35893896, 2022). "Materials and methods: Using cBioPortal breast cancer patient data, Kaplan–Meier plots demonstrated that high ATP2A1 and ATP2A3 expression was associated with reduced patient survival." (PMID 34684111, 2021). "In contrast, ATP2A3 overexpression reduces cell viability by promoting apoptosis in breast cancer cell lines." (PMID 34684111, 2021). "The ATP2A3 gene plays a significant role in intracellular Ca2+ management and normal cell death process, and transcriptional down-regulation of ATP2A3 has been identified in various cancers including breast cancer." (PMID 32183060, 2020). "Moreover, bioinformatics analysis indicated that ATP2A1 and ATP2A3 expression was highly altered in patients with breast cancer." (PMID 34684111, 2021). "Furthermore, resveratrol can induce the expression of ATPase sarcoplasmic/endoplasmic reticulum Ca2+ transporting 3 (ATP2A3, SERCA3) in breast cancer cells." (PMID 33806009, 2021). "Furthermore, HDAC inhibitors enhanced the expression levels of ATP2A3 in breast cancer." (PMID 32183060, 2020).
colon carcinoma (11 papers, 2012 to 2023). "For example, the SERCA3 gene (ATP2A3) exhibits hypermethylation and decreased expression in colon cancer: patients with low expression levels of SERCA3 displayed an average survival of 16.6 months, whereas patients with high expression levels survived 26.7 months." (PMID 35309905, 2022). "Epigenetic silencing of gene ATP2A3, which codes for SERCA3, is down-regulated in gastric and colon tumors." (PMID 31226817, 2019).
heart failure (4 papers, 2018 to 2025). Inability of the heart to pump blood at an adequate rate to meet tissue metabolic requirements. "Analysis of gene function revealed that CACNA1S, ATP2A3, and MYH7 were involved in cardiac muscle contraction and adrenergic signaling in cardiomyocytes, both of which are associated with heart failure and other diseases." (PMID 40029616, 2025). "Cardiac failure in severe COVID-19 has been reported, hence, ATP2A3 may be involved as it regulates cardiomyocyte contraction." (PMID 35239653, 2022).
Parkinson disease (4 papers, 2018 to 2025). A progressive degenerative disorder of the central nervous system characterized by loss of dopamine producing neurons in the substantia nigra and the presence of Lewy bodies in the substantia nigra and locus coeruleus. "ATP2A3 encodes a sarcoplasmic/endoplasmic reticulum Ca2+ ATPase and disorders of Purkinje cell and dopaminergic (Surmeier, Halliday, & Simuni, 2017) calcium homeostasis have been linked to dystonia and Parkinson disease, respectively." (PMID 29770609, 2018). "ATP2A3 is highly expressed in cerebellar Purkinje cells (Allen Brain Atlas) and is a member of the P‐type ATPase superfamily that includes the gene (ATP1A3) causally associated with rapid‐onset dystonia‐Parkinsonism (DYT12)." (PMID 29770609, 2018).
lung carcinoma (3 papers, 2013 to 2020). "Expression of ATP2A3 has also been reported to be dramatically reduced in human colon, breast, and lung cancers." (PMID 30918657, 2019).
central nervous system cancer (2 papers, 2017 to 2018). "Out of other candidates, ATP2A3 has been shown to be mutated and downregulated in HNSCC, lung, colon and central nervous system cancers." (PMID 28146432, 2017).
COVID-19 (2 papers, 2022 to 2024). A disease caused by infection with severe acute respiratory syndrome coronavirus 2. "Note that ATP2A3 has previously been genetically associated with severe COVID-19, but its exact role in infection remains unclear." (PMID 35239653, 2022). "Higher levels of LCTL, SFTPD, KEL, and ATP2A3 were solely associated with a decreased risk of hospitalization (ORs = 0.86–0.93), whilst higher levels of ICAM-1 were solely associated with a decreased risk of respiratory support/death of COVID-19 (OR = 0.84)." (PMID 35239653, 2022). "Furthermore, there were undetectable expression levels of ATP2A1, ATP2A3, ATP2B2, and ATP2B3 in the lungs of both COVID-19 patients and controls (Fig. EV1G)." (PMID 38816514, 2024). "Our sensitivity analyses confirmed the robustness of the association between 14 out of 15 blood markers and hospitalized-COVID-19, with ATP2A3 not satisfying the sensitivity analysis criteria (for a full breakdown of these sensitivity analyses)." (PMID 35239653, 2022).
prostate carcinoma (2 papers, 2015 to 2019). A carcinoma that arises from epithelial cells of the prostate gland. "In conclusion, our results suggest that salinomycin can upregulate ATP2A3 expression, which triggers ER stress to exert anti-cancer effects in prostate cancer cells." (PMID 31023247, 2019). "ATP2A3 was slightly expressed, but the ER stress biomarkers showed strong staining in prostate cancer tissues." (PMID 31023247, 2019). "We found that ATP2A3 was slightly expressed in human prostate cancer tissues, which suggested that the expression of ATP2A3 might be correlated with prostate tumorigenesis." (PMID 31023247, 2019). "To further confirm the role of ATP2A3, we overexpressed ATP2A3 in prostate cancer cells." (PMID 31023247, 2019). "Thus we analyzed the effect of ATP2A3 overexpression on ER stress in prostate cancer." (PMID 31023247, 2019). "Immunohistochemistry staining was used to evaluate the expression of ATP2A3 and ER stress biomarkers (BIP and ATF4) in human prostate cancer and para-carcinoma tissues." (PMID 31023247, 2019). "Our results showed that salinomycin upregulated the expression of ATP2A3 in PC-3 and DU145 prostate cancer cells." (PMID 31023247, 2019). "Thus, we investigated the effects of ATP2A3 in PC-3 and DU145 prostate cancer cells." (PMID 31023247, 2019).
bladder cancer (1 paper, 2023). "Compared with the expression levels in SV-HUC-1 uroepithelial cells, ATP2A3 and VWF were meaningfully low expressed in 4 bladder cancer cell lines (T24, 253J-BV, EJ, UMUC3), while P4HB were high." (PMID 37091788, 2023).
blepharospasm (1 paper, 2019). "Interestingly, a recent study showed that deleterious variants in CACNA1A, REEP4, TOR2A, ATP2A3, HS1BP3, GNA14, and DNAH17 were involved in blepharospasm, and none of these variants except for CACNA1A has been reported to be associated with blepharospasm." (PMID 32038460, 2019).
cervical cancer (1 paper, 2021). A primary or metastatic malignant neoplasm involving the cervix. "The overexpression of ITM2A, ATP2A3, and tumor suppressor gene SFRP1 is also closely related to a better prognosis of cervical cancer." (PMID 34030694, 2021).
colon adenocarcinoma (1 paper, 2023). "Compared with tumor adjacent tissues, EEF1A2, PBK and TIMP1 showed significant upregulation in colon adenocarcinoma, while ATP2A3, CDC25C, MMP3 and NAT1 showed significant downregulation." (PMID 37626132, 2023).
gastro-esophageal reflux (1 paper, 2011). "The results support the deduction that BE is a tissue with enhanced glycoprotein synthesis machinery (DPP4, ATP2A3, AGR2) designed to provide strong mucosal defenses aimed at resisting gastro-esophageal reflux." (PMID 21829465, 2011).
polyp (1 paper, 2022). A usually exophytic mass attached to the underlying tissue by a broad base or a thin stalk. "A significant difference in the expression of ELOVL6 and ATP2A3 was observed in tissues of patients with polyp and patients with COAD (P< 0.001 and P< 0.05, respectively)." (PMID 36532007, 2022).
retinal degeneration (1 paper, 2025). Degeneration of the retina. "Impaired expression or function of ATP2A3 may exacerbate ER stress, thereby activating proapoptotic pathways that accelerate retinal degeneration." (PMID 40548296, 2025).
uremia (1 paper, 2013). A clinical syndrome associated with the retention of renal waste products or uremic toxins in the blood. "The effect of uremia on platelet function may be reflected by changes in the probe sets coding for PKCeta, Rac1, ATP2A3, and GP-IB (platelet glycoprotein I beta) and other members of the “platelet aggregation” network." (PMID 23809614, 2013).
virus infection (1 paper, 2022). "Sarcoplasmic/endoplasmic reticulum calcium ATPase 3 (ATP2A3) is involved in numerous cancers, but we are not aware of any association with virus infection." (PMID 36299731, 2022).
cancer (24 papers, 2012 to 2025). A tumor composed of atypical neoplastic, often pleomorphic cells that invade other tissues. "ATP2A3 alteration has been reported in various types of tumors, and is involved in the susceptibility to multiple cancers in humans as a consequence of modulation of gene transcription and cell proliferation." (PMID 37353812, 2023). "Machine learning analysis pinpointed 14 feature genes, among seven were associated with cancer (NAT1, BIRC3, EZH2, MAD2L1, ATP2A3, HMGA1, and BST2)." (PMID 41255601, 2025). "Database searches indicated that NAT1, BIRC3, EZH2, MAD2L1, ATP2A3, HMGA1, and BST2 are cancer-associated genes." (PMID 41255601, 2025). "The data showed weak ATP2A3 staining, but the ER stress biomarkers were strongly stained in cancer tissues." (PMID 31023247, 2019). "Among these, NAT1, BIRC3, EZH2, MAD2L1, ATP2A3, HMGA1, and BST2 are known cancer-associated genes." (PMID 41255601, 2025). "In subsequent studies, we found that ATP2A3 overexpression could trigger ER stress and exert anti-cancer effects in PC-3 and DU145 cells." (PMID 31023247, 2019). "We further identified ATP2A3 as a potential target for the molecular mechanism of salinomycin, which might inhibit Ca2+ release and trigger ER stress to exert its anti-cancer effects." (PMID 31023247, 2019). "This study demonstrates that ATP2A3 might be one of the potential targets for salinomycin, which can inhibit Ca2+ release and trigger ER stress to exert anti-cancer effects." (PMID 31023247, 2019). "Some genes consistently indicated a positive prognosis in different cancer types, such as CD20, ADAM28, MEF2C, CPNE5, and ATP2A3." (PMID 35634306, 2022). "Several previous studies support the findings of the present study, including the link between ATP2B2 and ATP2A3 in cancer, as well as the hypothesis that ATP2B3 might serve as a possible cancer biomarker." (PMID 34684111, 2021).
tumor (14 papers, 2012 to 2025). "These dual roles—governing both tumor biology and immune homeostasis—underscore ATP2A3 as a promising therapeutic target." (PMID 40548296, 2025). "In cancer, downregulation of ATP2A3 has been reported across multiple tumor types." (PMID 40548296, 2025). "In addition, we found downregulated expression of ATP2A3, VWF in tumor tissues." (PMID 37091788, 2023).
ATP2A3 also shares sentences with these, for which no sentence is quoted: adenocarcinoma (5 papers); acute promyelocytic leukemia (4); diabetes (4); ductal carcinomas (4); gastric carcinoma (4); infection (4); leukemia (4); Sepsis (3); type 2 diabetes (3); acute lymphoblastic leukemia (2); adenoma (2); adenosis (2); Burkitt lymphoma (2); cardiac hypertrophy (2); choroid plexus tumors (2); colon (2); Hyperglycemia (2); lobular carcinoma (2); lymphoma (2); acrokeratosis verruciformis (1); acute myeloid leukemia (1); adenoid cystic carcinoma (1); asthma (1); autism (1); bipolar disorder (1); Brody disease (1); chronic kidney disease (1); colon adenoma (1); colorectal cancer (1); Darier disease (1).
A further 29 diseases each share a sentence with ATP2A3 in 1 paper.